SRPX2 (sushi repeat containing protein X-linked 2)
Description:
Acts as a ligand for the urokinase plasminogen activator surface receptor. Plays a role in angiogenesis by inducing endothelial cell migration and the formation of vascular network (cords). Involved in cellular migration and adhesion. Increases the phosphorylation levels of FAK. Interacts with and increases the mitogenic activity of HGF. Promotes synapse formation. May have a role in the perisylvian region, critical for language and cognitive development.
Synonyms: SRPUL; BPP; CBPS; PMGX; RESDX
Tractability: Antibody: UniProt places it where antibodies can reach, with high confidence; UniProt predicts a signal peptide or a membrane-spanning region; its Gene Ontology location is reachable by antibodies, with medium confidence.
Gene: Protein-coding gene on chromosome X (100,644,195 to 100,675,788, forward strand). Ensembl gene ENSG00000102359.
Subcellular location: Secreted; Cytoplasm; Cell surface; Synapse
Gene Ontology:
Molecular function: hepatocyte growth factor binding; identical protein binding; protein binding; signaling receptor binding; extracellular matrix structural constituent
Biological process: cell motility; cell-cell adhesion; positive regulation of synapse assembly; regulation of phosphorylation; positive regulation of cell migration involved in sprouting angiogenesis; regulation of synapse assembly; vocalization behavior
Cellular component: cytoplasm; extracellular matrix; extracellular region; cell surface; excitatory synapse; synaptic membrane; glutamatergic synapse; synapse
Gene-disease validity (ClinGen):
ClinGen rates the evidence that SRPX2 causes each of these diseases.
epilepsy (X-linked): Refuted. A brain disorder characterized by episodes of abnormally increased neuronal discharge resulting in transient episodes of sensory or motor neurological dysfunction, or psychic dysfunction.
Homologues: Orthologues: macaque Srpx2 (99% identical), dog SRPX2 (97% identical), pig SRPX2 (97% identical), rabbit SRPX2 (95% identical), chimpanzee SRPX2 (94% identical), mouse Srpx2 (94% identical), rat Srpx2 (94% identical), guinea pig SRPX2 (92% identical), tropical clawed frog srpx2 (60% identical), zebrafish srpx2 (53% identical). Paralogues in human: SRPX (45% identical), CFH (22% identical), F13B (18% identical), CSMD3 (16% identical), PAPPA (16% identical), CFHR5 (15% identical), CSMD1 (15% identical), SVEP1 (15% identical), PAPPA2 (14% identical), CSMD2 (14% identical), CR1 (13% identical), SELP (13% identical), and 27 more.
Diseases named in the same sentence as SRPX2 in open-access papers:
SRPX2 is named in the same sentence as 57 diseases in open-access papers, as found by Europe PMC text mining. Sharing a sentence is not in itself a finding about the gene and the disease. The quoted sentences say what the papers report.
epilepsy (11 papers, 2012 to 2025). "The SRPX2 gene, responsible for encoding a unique chondroitin sulfate proteoglycan, has been identified as playing a role in mediating seizure disorders, angiogenesis, and cellular adhesion." (PMID 39624823, 2024). "For example, polymorphisms of Plaur and the uPAR ligand sushi repeat containing protein X-linked 2 (encoded by the SRPX2 gene) correlate with human diseases such as epilepsy, autism, multiple sclerosis, Alzheimer’s disease and brain tumors." (PMID 35875662, 2022). "In humans, mutations in the CCP domain-containing secreted protein SRPX2 are associated with epilepsy and speech dysfunction, and SRPX2 knockdown leads to decreased synapse number and vocalization in mice." (PMID 33661101, 2021). "Several of these genes have been associated with neurological diseases such as epilepsy and schizophrenia, including SRPX2." (PMID 29920554, 2018). "SEZ6L2 (Seizure related 6 homolog (mouse)-Like 2) encodes a cell surface protein that has a strong homology with SRPX2 (Sushi-repeat-containing protein, X-linked), mutations in which cause epilepsy and language disorders." (PMID 26872257, 2016). "SRPX2 (Sushi repeat-containing protein, X-linked 2) has recently emerged as a multifunctional protein that is involved in seizure disorders, angiogenesis and cellular adhesion." (PMID 22242148, 2012). "CACNB4, CLCN2, MAGI2, and SRPX2 variants have all been proposed as causes of epilepsy." (PMID 40492992, 2025). "In a separate study, genes associated with epilepsy-aphasia spectrum, that encode for elongator acetyltransferase complex subunit 4 (ELP4) and sushi-repeat containing protein X-linked 2 (SRPX2), were studied for their potential interactions in BECTS." (PMID 30319421, 2018). "For example, the following genes were previously thought to be associated with epilepsy: EFHC1, SCN9A, CLCN2, GABRD, SRPX2 and CACNA1H." (PMID 28558813, 2017).
pancreatic cancer (9 papers, 2020 to 2022). "SRPX2 is an abnormal expression in a variety of cancers, such as pancreatic cancer, colorectal cancer, and gastric cancer." (PMID 35935582, 2022). "Further study indicated that silencing of SRPX2 sensitized pancreatic cancer cells against 5-Fu and gemcitabine by deactivating the PI3K/AKT/mTOR signaling pathway." (PMID 35935582, 2022). "SRPX2 is a component of the extracellular matrix, which is important for regulating tumor formation, as demonstrated in diverse tumors, such as colorectal cancer, gastrointestinal cancer, prostate cancer, and pancreatic cancer." (PMID 34660598, 2021). "This investigation was aimed at disclosing whether SRPX2 affected pancreatic cancer (PC) chemoresistance by regulating PI3K/Akt/mTOR signaling." (PMID 33336063, 2020). "SRPX2 has also been shown to confer chemoresistance for 5-Fu and gemcitabine by activating the PI3K/AKT axis in pancreatic cancer." (PMID 35267540, 2022). "SRPX2 is invasive by upregulating the FAK/SRC/ERK pathway and can lead to pancreatic cancer drug resistance in PI3K/AKT in lung cancer." (PMID 34660598, 2021). "For example, the combination of SRPX2 and RAB31 may be an important prognostic marker for pancreatic cancer, with a 3-year AUC value of 0.748." (PMID 33550277, 2021).
glioblastoma (8 papers, 2010 to 2023). The most malignant astrocytic tumor (WHO grade IV). "Further, SRPX2 expression is implicated in poor prognoses of cancer of the stomach, pancreas, liver, and prostate, and in glioblastoma and osteosarcoma." (PMID 32455867, 2020). "This set included SRPX2, as significantly linked to poor glioblastoma prognosis (t-test p-value 0.024)." (PMID 20964819, 2010). "At functional level, increased invasiveness, at least in part mediated by SRPX2, and macrophage infiltration characterise this subset of glioblastoma." (PMID 36412091, 2022). "Among these, SRPX2 plays a role in invasive properties of BE-GICs, raising the possibility that SRPX2 could be further explored as a potential therapeutic target for glioblastoma with a hypo-methylation bias and ACS enrichment." (PMID 36412091, 2022). "In glioblastoma, SRPX2 knockdown significantly decreased the expression of EMT markers (N-cadherin, fibronectin, Twist, Snail, and Slug) and increased E-cadherin expression, while SRPX2 overexpression increased N-cadherin and fibronectin expression and decreased E-cadherin expression." (PMID 35935582, 2022). "Here SRPX2, a significant portion of ECM, was introduced, and it has been acknowledged to reinforce chemotolerance of tumors, such as temozolomide-resistance of glioblastoma and cisplatin-resistance of esophageal cancer." (PMID 33336063, 2020). "Given our limited cohort size, the deregulation of SRPX2 was further validated in other datasets and found that it was more highly expressed in glioblastoma tumour tissue as compared to non-tumour brain tissue according to TCGA data and in BE-GICs from the HGCC cohort." (PMID 36412091, 2022). "Given that gliomas invade mainly along two routes, the white matter tracts and the blood vessels, it could be speculated that SRPX2 may play a role in the latter and not the former in the subset of glioblastoma with hypomethylation bias/astrocytic signature enrichment." (PMID 36412091, 2022).
colorectal cancer (7 papers, 2014 to 2024). A primary or metastatic malignant neoplasm that affects the colon or rectum. "SRPX2 overexpression plays a malignant role in colorectal cancer by regulating cell proliferation, adhesion, migration, and invasion." (PMID 37306872, 2023). "SRPX2 is a component in an extracellular matrix which involved in tumor formation including colorectal cancer, gastrointestinal cancer, and prostate cancer." (PMID 36385962, 2022). "The metastasis-promoting role of SRPX2 was also manifested in colorectal cancer and liver cancer, which highlighted the oncogenic part of SRPX2." (PMID 33336063, 2020). "Besides, SRPX2 is highly expressed in cancer tissues and cell lines, including glioma, mesothelioma, osteosarcoma, esophageal, gastric, lung, and colorectal cancers." (PMID 37306872, 2023). "Moreover, the inhibition of SRPX2 by siRNA also inhibited the invasion of colorectal cancer HCT116 cells through downregulating Wnt/β-catenin pathway-mediated MMP2/9 expression." (PMID 35935582, 2022). "SRPX2 and FOXM1 were proven to be directly regulated by mir-149 in colorectal cancer and lung cancer, respectively." (PMID 25405731, 2014).
gastric cancer (7 papers, 2010 to 2022). A primary or metastatic malignant neoplasm involving the stomach. "Recently, we demonstrated that SRPX2 is overexpressed in gastric cancer tissue and that expression was associated with a poor clinical outcome." (PMID 22242148, 2012). "It has been suggested that SRPX2 might be treated as a prognostic biomarker associated with a malignant gastric cancer phenotype." (PMID 20964819, 2010). "Then, a novel TGF-β-associated prognostic model, including SRPX2, SGCE, DES, MMP7, and KRT17, was constructed, and the risk score was demonstrated as an independent prognostic factor for gastric cancer patients." (PMID 36467074, 2022). "Sushi repeat-containing protein X-linked 2 (SRPX2), a chondroitin sulfate proteoglycan, is highly expressed in a variety of cancers, including esophageal squamous carcinoma or gastric cancer." (PMID 36385962, 2022). "Studies have shown that SRPX2 is highly expressed in gastric cancer and can promote migration and adhesion of gastric cancer cells, which is closely associated with poor prognosis of gastric cancer patients." (PMID 36467074, 2022). "Researchers showed that elevated SRPX2 in gastric cancer and pancreatic ductal adenocarcinoma enhanced migration and adhesion through increasing phosphorylation levels of FAK." (PMID 35935582, 2022). "SRPX2 enhances cellular migration and adhesion in gastric cancer cells and, interestingly, the conditioned-medium obtained from SRPX2-producing cells increased the cellular migration activity and cellular adhesion." (PMID 22242148, 2012). "Of note, prognosis in gastric cancer is related to SRPX2 expression (patients with unfavorable prognosis had significantly higher SRPX2 expression than those with more favorable one)." (PMID 20964819, 2010). "Moreover, it was also reported that gastric cancer patients with overexpression of SRPX2 presented a lower OS and worse prognosis in comparison to patients with low SPRX2, and SRPX2 was considered a useful independent predictor of outcomes." (PMID 35935582, 2022). "In this study, we detected the expression levels of KAP1, TIMP1, STC2, TLN2, SRPX2 and SPARC mRNAs in peripheral blood samples from pre-operative gastric cancer patients, those with recurrence, and in healthy volunteers." (PMID 23548070, 2013). "In this study, we detected the expression of KAP1, TIMP1, STC2, TLN2, SRPX2, integrin beta 1 (ITGB1) and SPARC mRNAs in peripheral blood samples from pre-operative gastric cancer patients, patients with recurrence, and healthy volunteers." (PMID 23548070, 2013). "Our study showed that TLN2, SRPX2 and SPARC expression were detected in gastric cancer, but expression of TLN2, SRPX2 and SPARC could not differentiate preoperative gastric cancer patients from healthy volunteers." (PMID 23548070, 2013). "Previous studies have shown that SRPX2 and SPARC were overexpressed in gastric cancer tissues, while TLN2 was upregulated in breast carcinomas tissues; however, no studies investigating the expression of TLN2, SRPX2, and SPARC in peripheral blood have been reported." (PMID 23548070, 2013).
glioma (7 papers, 2010 to 2025). A benign or malignant brain and spinal cord tumor that arises from glial cells (astrocytes, oligodendrocytes, ependymal cells). "SRPX2 is found among their top regulated genes, (q-value 0.0069, average fold change glioma vs normal: 2.4)." (PMID 20964819, 2010). "Moreover, MRI inputs integrated into machine learning models can predict genomic features and differentiate between low- and high-grade gliomas by identifying markers such as B2M, SRPX2, and SERPINH1." (PMID 40806525, 2025). "CENPA, COL3A1, GRP65, SRPX2 and GPX8 were upregulated in glioma, while remaining genes were downregulated." (PMID 39620895, 2024). "Quantitative PCR and immunohistochemical analysis showed that LIF, LOX, MMP9, S100A4, SRPX2, and TIMP1 were expressed at high levels in glioma, whereas SLITI1 and SMOC1 were expressed at low levels, consistent with our previous results." (PMID 36560848, 2023). "Mutations in XIE genes USP9X, NLGN4x, PLXNB3 (involved in axonal guidance and glioma invasion), SYAP1, SRPX2, and ZFX (ZFX-SMARCA1 fusion) occurred in non-MN1-BEND2, predominantly female cases." (PMID 35440587, 2022).
colon cancer (6 papers, 2020 to 2022). "miR-215-5p and miR-192-5p regulate glycolysis in colon cancer cells through Sushi Repeat Containing Protein X-Linked 2 (SRPX2) expression, and downregulation of these miRNAs is promoted by PI3K-AKT pathway." (PMID 33575847, 2021). "Additionally, miR-192-5p represses glycolysis by regulating the expression of sushi repeat-containing protein X-linked 2 (SRPX2) in colon cancer cells." (PMID 33708127, 2021). "SRPX2 supported colon cancer cell glycolysis through miR-192 and miR-215, both of which are suppressed by PI3K-Akt." (PMID 36483029, 2022). "miR-192 also benefits the prognosis of colon cancer patients by regulating SRPX2, Rab-2A, RhoA-ROCK-LIMK2, farnesoid X receptor, RB1/E2F1 pathway, and NOD2." (PMID 33614788, 2021).
language disorder (6 papers, 2016 to 2024). A category of disorders characterized by an impairment in the development of an individual's language capabilities, which is in contrast to his/her non-verbal intellect. "SRPX2 is a synaptogenic factor that critically contributes to the pathogenesis of language disorders, while it is also implicated in cell adhesion, migration and invasion, angiogenesis, resistance to therapy and epithelial to mesenchymal transition." (PMID 30795533, 2019). "Dysfunction of Sushi repeat containing protein X-linked 2 (SRPX2), which regulates synaptogenesis in cortical neurons, is associated with intellectual disability and language disorder." (PMID 31841517, 2019).
Rolandic epilepsy (5 papers, 2014 to 2022). "Moreover, alterations in the SRPX2 gene are associated with bilateral perisylvian polymicrogyria, rolandic epilepsy, speech dyspraxia and mental retardation." (PMID 29244816, 2017). "Disruption of SRPX2 is associated with Rolandic epilepsy, speech dyspraxia and ID." (PMID 24699272, 2014).
esophageal cancer (4 papers, 2020 to 2023). A primary or metastatic malignant neoplasm involving the esophagus. "Previous studies have shown that Sushi Repeat Containing Protein X-linked 2 (SRPX2) acts as a tumor-promoting factor in various cancers, and the down-regulation of SRPX2 can improve the sensitivity of esophageal cancer patients to cisplatin." (PMID 37803421, 2023). "Recent reports have revealed that the downregulation of SRPX2 increases chemosensitivity to cisplatin in esophageal cancer." (PMID 32455867, 2020). "Since SRPX2 is related to cisplatin resistance in esophageal cancer cells, we finally verified the effects of SRPX2 on OSCC cell tolerance to platinum anticancer drugs." (PMID 32455867, 2020).
hepatocellular carcinoma (4 papers, 2022 to 2023). A malignant tumor that arises from hepatocytes. "SRPX2 expedites hepatocellular carcinoma by targeting the FAK/AKT pathway and regulating the expression of MMP2/9." (PMID 36385962, 2022). "In hepatocellular carcinoma, SRPX2 knockdown suppressed pulmonary metastasis of hepatocellular carcinoma HCCLM3 cells in nude mice, which the mechanisms were through inhibiting FAK/AKT pathway-mediated MMP2/9 expression." (PMID 35935582, 2022).